BDNF (brain derived neurotrophic factor)
Diseases named in the same sentence as BDNF in open-access papers (continued):
Sharing a sentence is not in itself a finding about the gene and the disease.
psychiatric disorder (569 papers, 2008 to 2026). A disorder characterized by behavioral and/or psychological abnormalities, often accompanied by physical symptoms. "Dysregulation of BDNF signaling has been implicated in psychiatric disorders, such as depression 9, schizophrenia 9, and addiction." (PMID 39868120, 2025). "The Val66Met polymorphism, which affects activity-dependent BDNF secretion, has been implicated in susceptibility to neurodegenerative and psychiatric disorders." (PMID 41227085, 2025). "Since BDNF acts as an upstream regulator of Akt and promotes the activation of its signaling pathway, Akt has also been implicated in psychiatric disorders." (PMID 41141866, 2025). "Several studies have investigated the association between human serum BDNF levels and psychiatric disorders." (PMID 39941545, 2025). "The Val66Met polymorphism of the BDNF gene is widely implicated in several psychiatric disorders, being associated with some changes in hippocampal volume with HPA axis activity, major depression, anxiety, unipolar disorder and bipolar disorder, respectively." (PMID 40869374, 2025). "BDNF downregulation plays a key regulatory role during neuronal plasticity development and is associated with psychiatric disorders." (PMID 41244820, 2025). "Extensive studies have been carried out to explore the mechanism underlying the psychiatric disorders including the antidepressive effects for SCFAs, such as synapse plasticity involving BDNF, neuroinflammation suppression, and neurotransmitter." (PMID 38939042, 2024). "The molecule BDNF has been intensively studied as an antidepressant drug, and the BDNF gene is known as a common genetic locus of risk for mental illness." (PMID 38994950, 2024). "Abnormalities in BDNF epigenetic regulation, transport, or signalling pathways have been linked to various neurological and psychiatric disorders." (PMID 39063164, 2024). "Brain‐derived neurotrophic factor (BDNF)contributes to neuronal growth and synaptic function via tyrosine kinase receptor B (TrkB) receptor activation and is linked to psychiatric disorder pathogenesis." (PMID 38992889, 2024). "This appears to be highly relevant to the discourse in this article as patients diagnosed with psychiatric disorders show decreased neural BDNF levels, often associated with increased DNA methylation at specific BDNF promoters." (PMID 39268220, 2024). "Fluctuations in BDNF levels are closely associated with several neurological and psychiatric disorders." (PMID 39684808, 2024). "These analyses confirmed a significant association (P < 0.05) between the BDNF Val66Met polymorphism and weight shifts in individuals with psychiatric disorders who share the polymorphism, as evidenced by their similar average BMIs." (PMID 38988887, 2024). "As already mentioned, the human Val66Met polymorphism in the BDNF gene is associated with mental illnesses and disturbances." (PMID 39194496, 2024). "This review investigated the effects and underlying mechanisms by which the BDNF Val66Met polymorphism moderates body weight among individuals with psychiatric disorders." (PMID 38988887, 2024). "The link between BDNF rs6265 polymorphisms and psychiatric disorders was also revealed in studies that investigated the Russian population." (PMID 38397229, 2024). "Concurrently, a broad spectrum of research demonstrates that the BDNF Val66Met polymorphism is implicated in heightened vulnerability to psychiatric disorders, which span a diverse array of mental health challenges impacting mood, cognition, and behavior." (PMID 38988887, 2024). "The Val66Met polymorphism is a common variant of the BDNF gene (rs6265) which reduces activity-dependent BDNF release, and has been suggested as a risk factor for psychiatric disorders and substance use." (PMID 37372084, 2023). "Recent evidence suggests that BDNF plays a role in fear memory consolidation and extinction learning, orchestrating sensitivity to stress, trauma, and risk of stress-related psychiatric disorders." (PMID 36806044, 2023).
psychiatric disorder (continued). "The possible changes in BDNF have been proven, so it would be crucial to study these variants’ involvement in psychiatric disorders pathogenesis in large case-control samples." (PMID 37644489, 2023). "Brain-derived neurotrophic factor (BDNF) is the most well-studied neurotrophin and has been implicated in the pathogenesis of various psychiatric disorders, including MDD." (PMID 37626579, 2023). "In contrast, plasma concentrations of GDNF and BDNF/proBDNF were reduced in individuals with psychiatric disorders and those with suicides caused by life events." (PMID 37509026, 2023). "Alterations in the BDNF gene have been associated with several neurological and psychiatric disorders." (PMID 37759083, 2023). "Some studies show that BDNF methylation CpG regions have been linked to cognitive deficits and psychiatric diseases." (PMID 37008217, 2023). "While, a defect in the regulation of BDNF release can cause abnormalities in the underlying brain processes and cognitive dysfunctions in the psychiatric disorders." (PMID 36641432, 2023). "The human genetic variant BDNF (V66M) represents the first example of neurotrophin family member that has been linked to psychiatric disorders." (PMID 35743044, 2022). "Since we know that BDNF expression has been associated with both normal and pathological aging, psychiatric disease, and cognitive and neurodegenerative diseases, we evaluated the BDNF protein level in the injured SH-SY5Y cell line using ELISA assay." (PMID 36233079, 2022). "As such, disruption of BDNF sorting and/or secretion has been implicated in various neurodegenerative and psychiatric diseases." (PMID 35887357, 2022). "BDNF exon IV promoter methylation has been associated with multiple psychiatric disorders along with MDD as well as treatment response to ADs and other available therapy regimens." (PMID 36572893, 2022). "1-3 Consistent evidence shows changes in BDNF regulation underlying several behaviors and psychiatric disorders." (PMID 34060728, 2022). "In a subsequent study, rats deficient in brain-derived neurotrophic factor (BDNF), a chemical signal associated with psychiatric disorders, were tested for conditioned fear during imaging." (PMID 35450017, 2022). "BDNF plays a role in resilience and antidepressant drug action; it is a common genetic locus of risk for mental illnesses and is one of the most prominently psychiatric-studied molecules." (PMID 36611538, 2022). "Stress, which probably is the “lowest common denominator” risk factor for several mental illnesses, targets BDNF in disease-implicated brain regions and circuits." (PMID 36611538, 2022). "Deficiency of neurotrophin and/or disturbances in BDNF/TrkB/p75NTR—dependent signaling contributes to pathogenesis and progression of numerous neurological and psychiatric disorders, denoting protective and regenerative properties of BDNF8." (PMID 33833366, 2021). "It affects neuronal maturation, formation of synapses and synaptic plasticity BDNF is also associated with the development of psychiatric disorders." (PMID 34362162, 2021). "Polymorphism in BDNF pro-domain, resulting in Val66Met substitution, is known to affect BDNF processing and secretion and associated with psychiatric disorders." (PMID 34495310, 2021). "BDNF plays a critical role in development and plasticity of the brain and is implicated in the pathology of many psychiatric disorders." (PMID 35087430, 2021). "Although aberrant BDNF/TrkB signaling is implicated in several neurological, neurodegenerative and psychiatric disorders, neurotrophin-based therapy is challenging and is limited by improper pharmacokinetic properties of BDNF." (PMID 33833366, 2021). "Through epidemiological studies, there is substantial supporting evidence that psychiatric disorders are associated with cardiac diseases via BDNF." (PMID 34827728, 2021).
psychiatric disorder (continued). "Aging is characterized by a decrease in BDNF concentrations, and chronic BDNF deficiency in the hippocampus induces cognitive dysfunction, in which BDNF dysregulation has been implicated in aging-associated psychiatric disorders." (PMID 32245093, 2020). "A number of studies have demonstrated that BDNF preferentially binds to the TrkB receptor, and dysfunction of the BDNF/TrkB system is associated with the pathophysiology of brain diseases, including neurodegenerative diseases and mental illness." (PMID 32185198, 2020). "The effects of these probiotics on psychiatric diseases are associated with BDNF, which plays an essential role in neuronal survival and neurogenesis in dentate gyrus of the hippocampus, and in new synapse formation for learning and memory." (PMID 32245093, 2020). "The alterations of BDNF expression in leukocytes are also associated with diverse psychiatric disorders, and changes of BDNF expression in plasma or serum are associated with various neurodegenerative diseases." (PMID 33375318, 2020). "Recent evidence has indicated that BDNF deficiency reduces neuroplasticity and leads to spatial memory impairment in aging rat hippocampi, and impaired regulation of BDNF has been implicated in aging-associated psychiatric disorders." (PMID 30875947, 2019). "Human populations with a genetic variant that decreases the BDNF concentration appear to be more susceptible to psychiatric disorders." (PMID 30117106, 2019). "We previously demonstrated that DNAm at sites in a smaller number of genes implicated in psychiatric disease (several BDNF-related and GABA-related genes) correlated strongly with local gene expression." (PMID 30696804, 2019). "Changes in BDNF expression are associated with both normal and pathological aging and also psychiatric disease, in particular in structures important for memory processes such as the hippocampus and parahippocampal areas." (PMID 31440144, 2019). "Antidepressant drugs or other treatments for mental disorders can restore the deficient peripheral and brain levels of BDNF and stimulate adult neurogenesis." (PMID 31118969, 2019). "Most positive association studies have reported that the Met allele is the risk allele for psychiatric disease given that Met carriers exhibit reduced activity-dependent secretion of BDNF." (PMID 29867348, 2018). "Specifically, the human BDNF polymorphism that converts the 66 position amino acid valine to a methionine (Val66Met) has been associated not only with mental illness risk, but also with memory." (PMID 29520222, 2018). "Compelling evidence has linked the pathogenesis of several major neurologic and psychiatric disorders to alterations in BDNF function." (PMID 35098038, 2017). "BDNF has been implicated to play a neuroprotective role in the central nerve system; low levels of BDNF have been associated with aging and an array of neurological and psychiatric disorders." (PMID 28056856, 2017). "Brain‐derived neurotrophic factor (BDNF) signaling is implicated in the etiology of many psychiatric disorders associated with altered emotional processing." (PMID 26586578, 2016). "This is especially important since growing evidence suggests a role for BDNF in the pathophysiology of brain-associated illnesses including both neurodegenerative and psychiatric diseases." (PMID 26869919, 2016). "Molecules like Brain Derived Neurotrophic Factor (BDNF) and progranulin are linked to the pathophysiology of both neurodegenerative and psychiatric diseases." (PMID 26869919, 2016). "Candidate genes such as the serotonin transporter SLC6A4 and BDNF have been highly implicated in stress response and in increased risk for psychiatric disorders." (PMID 26583053, 2015). "Abberant gene expression of brain-derived neurotrophic factor (BDNF) has been implicated in onset of several mental illnesses subsequent to early-life adversity." (PMID 24859147, 2014).
psychiatric disorder (continued). "For instance, regulation of gene expression for several genes, such as BDNF, has been previously implicated in various psychiatric disorders." (PMID 25414627, 2014). "BDNF was shown to protect neurons from various attacks, and it was associated with several psychiatric disorders such as substance-related disorders, eating disorders, and schizophrenia." (PMID 25364831, 2014). "The role of neurotrophins is crucial as decreases in BDNF levels are associated with age-related neuronal loss and BDNF reduction is also observed in patients affected by neurodegenerative or psychiatric disorders." (PMID 25228860, 2014). "The brain-derived neurotrophic factor (BDNF) is the most widely distributed neurotrophin in the brain, and it has been associated with several psychiatric disorders." (PMID 23785335, 2013). "The SNP results in (Val) to (Met) substitution in the proBDNF protein at codon 66, and is thought to be associated with low BDNF levels in psychiatric disorders." (PMID 25408895, 2013). "Our results concur with previous findings on BDNF polymorphisms and serotonergic drug responses in psychiatric disorder patients." (PMID 23593198, 2013). "Although BDNF lacks diagnostic specificity, findings of BDNF alterations across a number of psychiatric disorders, underscores the shared common pathophysiological mechanisms and high rates of comorbidity." (PMID 23908608, 2013). "Alterations in function of the neurotrophin BDNF are associated with neurodegeneration, cognitive decline, and psychiatric disorders." (PMID 23785422, 2013). "BDNF is involved in learning and memory formation and reduced BDNF levels in various brain regions have been implicated in the pathogenesis of neurodegenerative and psychiatric disorders." (PMID 20404913, 2010). "Variations in the gene for the brain-derived neurotrophic factor (BDNF) have been examined for associations between cognitive traits and psychiatric disorders." (PMID 19844571, 2009). "Brain-derived neurotrophic factor (BDNF) plays a crucial role in neuronal growth, differentiation, survival, and synaptic plasticity, and its dysregulation is implicated in the pathogenesis of various psychiatric disorders." (PMID 39997339, 2025). "Additionally, the BDNF Val66Met polymorphism also influences the trajectory of psychiatric disorders by affecting the development of particular brain regions, serum BDNF levels, interactions with other genes, and dietary habits." (PMID 38988887, 2024). "Additionally, reduced BDNF levels in both the central and peripheral systems have been closely linked to various neurogenic diseases, including neuropathic pain and psychiatric disorders." (PMID 39648800, 2024). "Being a crucial molecule in the development of neurons, BDNF performs vital roles in memory formation (spatial, long-term and emotional, particularly fear), which are linked to learning abilities; hence, BDNF is much implicated in psychiatric disorders." (PMID 38494488, 2024). "Furthermore, DNA methylation and DNA methyltransferases regulate neurogenesis through epigenetic control of gene expression, while neurogenesis is associated with psychiatric disorders and BDNF levels." (PMID 39268220, 2024). "There is growing evidence that lowered BDNF is associated with psychiatric disorders: “Dysregulation in 5-HT–BDNF [serotonin-BDNF] interaction may be responsible for development of neuropsychiatric and behavioral abnormalities”." (PMID 39484176, 2023). "Indeed, reduced levels of BDNF contribute to cerebral atrophy, cognitive decline, and the increased risk of psychiatric disorders." (PMID 37631295, 2023). "The hippocampal expression of BDNF decreases in response to chronic stress, and changes in BDNF expression have been strongly associated with both normal and pathological aging, particularly in structures essential for memory processes and psychiatric diseases." (PMID 37592949, 2023).
psychiatric disorder (continued). "Further research is needed to validate BDNF/BDNF-AS gene polymorphisms as biomarkers for psychiatric disorders, as it can potentially improve diagnostic accuracy and enable the personalization of therapeutic interventions based on individual genetic profiles in mental health disorders." (PMID 37763162, 2023). "Monitoring early motor developmental milestones and BDNF levels during childhood may still potentially assist in early identification of individuals at risk for psychiatric disorders." (PMID 37234686, 2023). "The BDNF–oxytocin link could have great potential for understanding the underlying mechanisms of various psychiatric disorders and should promote further investigation on the subject." (PMID 35888641, 2022). "BDNF is of interest to cortisol studies, as inhibition of glucocorticoid receptors indirectly disrupts BDNF signalling, which is implicated in issues with memory and development of mental illness." (PMID 35119793, 2022). "BDNF is also associated with the development of psychiatric disorders." (PMID 34362162, 2021). "BDNF rs6265 has pleiotropic effects in various psychiatric disorders and is associated with multiple phenotypes, and therefore, either A or G allele might exert beneficial or damaging effects." (PMID 33926045, 2021). "BDNF is highly expressed in the brain, associated with neuronal survival, neuronal maintenance, synaptic plasticity, etc., and is widely known to be associated with neuroinflammation and psychiatric disorders." (PMID 34944580, 2021). "Given the key role of BDNF-TrkB signaling in psychiatric disorders, it is likely that alterations in BDNF-TrkB signaling may contribute to anhedonia susceptibility to SNI surgery." (PMID 29882089, 2020). "This novel finding could be beneficial in deciphering the physiological processes underlying effective antidepressant mechanisms or psychiatric disorders involving BDNF/NTRK2 signaling." (PMID 30765816, 2019). "Overall, these results suggest that genetic variation in CACNA1C may contribute to risk for psychiatric disorders through impacting cognitive flexibility, and that at a molecular level, this may be in part caused by alterations in BDNF expression." (PMID 30304534, 2019). "This polymorphism impairs BDNF trafficking and synaptic localization, causes a reduction in activity-dependent BDNF secretion and is associated with alterations in brain structure and function leading to several neurological and psychiatric disorders." (PMID 31429825, 2019). "Numerous studies have associated BDNF with mental illnesses, including schizophrenia." (PMID 29520222, 2018). "Recent studies in humans and mutant mouse models provide supporting evidence for biological epistasis between BDNF and genes involved in serotonin regulation that may alter neural circuitry and thereby influence risk for psychiatric disease." (PMID 27695066, 2016). "This is an important difference given that serum BDNF levels may prove to be useful biomarkers of risk for psychiatric diseases in humans." (PMID 26586578, 2016). "Finally, altered BDNF/TrkB signaling has been implicated in the pathophysiology of neurodegenerative and psychiatric disorders including, AD, PD, HD, bipolar disease and epilepsy." (PMID 27555809, 2016). "BDNF has also been implicated in the neurobiological mechanisms of psychiatric diseases." (PMID 26388728, 2015). "Some studies have linked reduced levels of BDNF to psychiatric disorders and suicide." (PMID 25908105, 2015). "A mechanistic understanding of BDNF-endocannabinoid interactions regulating synaptic plasticity may provide clues to underlying pathologies of neurologic and psychiatric disorders and suggest novel strategies for therapeutic intervention." (PMID 25938134, 2015). "The Val66Met SNP in the BDNF gene has been shown to cause significant dysfunction in dendritic trafficking and activity-dependent secretion of BDNF, ultimately contributing to several neurologic and psychiatric diseases." (PMID 25309465, 2014).